EGFR (epidermal growth factor receptor)
Diseases named in the same sentence as EGFR in open-access papers (continued):
Sharing a sentence is not in itself a finding about the gene and the disease.
cancer (continued). "BRAF fusions have also been identified as mechanisms of secondary resistance after treatment of EGFR-driven cancer with tyrosine kinase inhibitors (TKIs)." (PMID 37509339, 2023). "Another paradoxical observation is the CAF-mediated EGFR signaling pathway, which seems to be essential for several cellular functions, including the maintenance of cancer stemness, cell proliferation and invasion, and metastasis." (PMID 38006033, 2023). "The present work aims to design a carrier-mediated delivery system specifically targeting cancer cells with EGFR and MET receptor cross-talk." (PMID 37631372, 2023). "For this reason, their inhibitors have been tested in many cancers, singly and in combinations with other drugs, including EGFR pathway-targeting drugs." (PMID 37296881, 2023). "Studies have shown that EGFR has pro-survival kinase-independent functions in cancerous cells, offering a new perspective on EGFR implications in malignancies and targeted cancer therapies." (PMID 37446288, 2023). "EGFR-TKIs, such as gefitinib, erlotinib, afatinib, dacomitinib and osimertinib, have improved the outcomes of EGFR-dependent cancers for many patients." (PMID 37528485, 2023). "Among the top 20 common KEGG pathways, pathways in cancer, proteoglycans in cancer, and EGFR tyrosine kinase inhibitor resistance, not only accounted for the highest gene ratio but also had the lowest p-value scores." (PMID 37809603, 2023). "We further explored the clinical potential of perilla phenols by assessing their use as an adjuvant therapy for reducing the doses of chemotherapy drugs and EGFR tyrosine kinase inhibitor (TKI) in cancer treatment." (PMID 37834377, 2023). "Many studies have confirmed that the EGFR/MAPK signaling pathway plays crucial roles in the regulation of cancer." (PMID 38143380, 2023). "Rather, cSNX1.3 seemed to only effect the retrograde trafficking of EGFR, further highlighting the importance of this pathway for the understanding and treatment of cancer." (PMID 37720348, 2023). "These MDs specifically targeted EGFR-overexpressing cancer cells (A549 and MDA-MB-468) while avoiding normal cells (16HBE)." (PMID 37173721, 2023). "Other investigators have reported similar findings, showing that STAT3 has been linked to EGFR, where EGFR can activate STAT3, thus contributing to cancer progression." (PMID 36977736, 2023). "Survival analysis of HCC patients (GSE10141) revealed that EGFR activation in cancer tissues was an independent prognostic factor in patients with HCC (p < 0.01)." (PMID 36831279, 2023). "PE38, which lacks an intrinsic cell-binding domain, binds to EGFR-expressing cancer cells via the TGFα moiety in the recombinant toxin." (PMID 36900277, 2023). "We propose a strategy of combining PARP inhibitors with bispecific antibodies that target both EGFR and Notch signalling, highlighting the difficulties posed by deregulation of Notch signalling and the enrichment of cancer stem cells (CSCs) during therapy." (PMID 37441599, 2023). "EGFR is highly expressed in certain cancer types and is involved in regulating the biological characteristics of cancer progression, including proliferation, metastasis, and drug resistance." (PMID 37623233, 2023). "Epidermal growth factor receptor is one of the proteins involved in cancer cell proliferation, differentiation, and invasion." (PMID 38137520, 2023). "JorA-induced significantly changed proteins were enriched in “cancer-related pathways” and “EGFR-related signaling pathways”, which mainly manifested by inhibiting cell proliferation and promoting cell apoptosis." (PMID 37587470, 2023). "Promising results with the fluorescently labeled anti-EGFR Nb 7D12-s775z in murine models motivated a project employing the compound in a pioneering study in dogs with spontaneous cancer." (PMID 37781693, 2023).
cancer (continued). "In this study, MT4-MMP was demonstrated to promote cancer cell proliferation only in 3D cell cultures and through the activation of the epidermal growth factor receptor (EGFR) after its binding to ligands." (PMID 37373092, 2023). "Coupling the targeting ability of antibodies with the drug delivery capabilities of NPs holds great promise for the treatment of various cancers, therefore prominent examples of EGFR-targeting NPs are detailed in the following sections." (PMID 37754880, 2023). "Wild-type amplification or constitutively active mutant of EGFR constantly transmits signal to downstream pathways to promote cancer initiation and progression." (PMID 37487081, 2023). "In preclinical studies, everolimus was shown to overcome EGFR drug resistance and provide a cooperative impact with EGFR inhibitors in various human cancer cell lines resistant to EGFR inhibitors." (PMID 36902280, 2023). "KRAS is a component of epidermal growth factor receptors (EGFR) signaling that are vital molecules in cancer therapy." (PMID 37371705, 2023). "Although targeted therapies against some of the major EMT-inducers have been vastly used to treat cancer patients (e.g., anti-EGFR tyrosine kinase inhibitors), others have repeatedly failed in clinical trials (e.g., anti-TGF-β inhibitors)." (PMID 38067168, 2023). "The overactivation of the EGFR pathway is recognized as an etiological factor in human cancer, contributing to cancer development, metastasis, and chemotherapy resistance." (PMID 37370896, 2023). "Because EGFR is frequently overexpressed in human tumors, there is a compelling reason to try to inhibit it in order to improve cancer treatment." (PMID 36768973, 2023). "This is consistent with an earlier report where mAb 425 and bsAb PD-L1xEGFR were compared for their ability to inhibit EGFR-mediated cancer cell proliferation." (PMID 37545491, 2023). "In different cancer models, Arc suppressed EGFR- and Her2-mediated signaling cascades, Akt/mTOR-, and STAT3/β-catenin-dependent pathways." (PMID 38001865, 2023). "This phenomenon of SCLC transformation in EGFR mutant cancers that have become resistant to TKIs was initially observed in isolated patient case reports and has subsequently been confirmed in multiple cohorts of patients who underwent repeat biopsies." (PMID 38188289, 2023). "For instance, the effects of the common overexpression of EGF receptor (EGFR) in cancer cells can be eliminated by the use of luteolin, which decreases the EGFR mRNA via the MAPK inhibition as well as the mTOR and Akt signaling pathways." (PMID 37958980, 2023). "For EGFR-expressing cancer cells, as in the case of NSCLC, a host of EGFR-binding ligands were developed to be conjugated onto NPs." (PMID 37754880, 2023). "EGFR-targeted therapies such as monoclonal antibodies and tyrosine kinase inhibitors are currently available therapeutics for EGFR-driven cancers." (PMID 38137520, 2023). "Since abnormal activation of EGFR is closely related to the development of cancer, many studies have been conducted on EGFR in targeted therapy." (PMID 36737605, 2023). "This mutation was identified during our previous clinical observation study, a biomarker research for anti-EGFR monoclonal antibodies in a comprehensive cancer genomics study of patients with CRC (BREAC)." (PMID 36856908, 2023). "One of the key cancer-related genes affecting NSCLC is the epidermal growth factor receptor (EGFR) gene." (PMID 36661704, 2023). "Targeting EGFR has currently become one of the major signal blockade strategies to treat patients with several cancers including OSCC." (PMID 37341071, 2023). "Aberrant EGFR is considered an etiological factor in human cancer, contributing to cancer development, metastasis, and resistance to chemotherapy." (PMID 37497406, 2023).
cancer (continued). "In 2011, the development of cationic SLN functionalized with a monoclonal antibody (mAb) directed against the epidermal growth factor receptor (EGFR) represented the first step in antibody-mediated strategies using drug-loaded SLN in cancer therapy." (PMID 36678845, 2023). "The aberrantly enhanced expression of the EGFR or its cognate ligands leads to the overactivation of the EGFR signaling pathway, which drives the development and progression of human cancers." (PMID 36677874, 2023). "After cancer recurrence, the PD-L1 was found to be up-regulated in patients treated with chemotherapy or EGFR-TKI therapy, but decreased in the patients with anti-PD1 therapy." (PMID 37152062, 2023). "One of the current strategies to manage cancer overgrowth is inhibiting a trans-membrane glycoprotein called Epidermal growth factor receptor (EGFR) due to its essential role in intracellular signalling, morphogenesis, and differentiation." (PMID 37548154, 2023). "In fact, the scFv structure originated from panitumumab monoclonal antibody was expressed on the surface of bacteria as a fusion with ClyA to interact with highly overexpressing EGFR cancer cells in vitro." (PMID 37775519, 2023). "Since Sorcin is overexpressed in different types of tumors and is involved in the calcium-linked regulation of pathways triggered by EGFR, we investigated the role of Sorcin in EGF-dependent invasion of cancer cells." (PMID 37442828, 2023). "The introduction of epidermal growth factor receptor (EGFR) recognition sequence on gelatin is used for gene delivery studies in the cancer cells of the pancreas." (PMID 36850121, 2023). "The EGFR is a tyrosine kinase receptor that regulates several processes including cell proliferation, differentiation, division, survival, and cancer development." (PMID 38196993, 2023). "Fucosylation, a modification of N-glycoprotein mediated by fucosyltransferase, is involved in cancer cell adhesion, motility, and cellular signaling by regulating the functions of glycoproteins such as EGFR and TGFBR." (PMID 37612293, 2023). "The epidermal growth factor receptor (EGFR), as the first tyrosine kinase receptor to be cloned, is still at the leading edge of targeted cancer therapy." (PMID 37304305, 2023). "EGFR is a transmembrane receptor which has a crucial function in cancer cell proliferation, neoangiogenesis and the inhibition of apoptosis." (PMID 37240224, 2023). "Here we describe that a wide spectrum of human cancers harbors a co-amplification of CBX3 gene with either EGFR or RAC1, which yields a statistically significant increase of both mRNA and protein levels of CBX3, EGFR and RAC1." (PMID 37633946, 2023). "Hyper-activation of EGFR signaling has been detected in several cancers, including colon, head and neck, ovarian, and breast cancers." (PMID 37495969, 2023). "Further, endocytosis is involved in activation of certain cancer receptors such as Epidermal growth factor receptor (EGFR), Transferrin receptor (TfR), and Notch receptor." (PMID 36769293, 2023). "In a recent phase I trial (NCT04820023), 25 patients with EGFR-mutant NSCLC who had cancer progression on at least one EGFR TKI were enrolled." (PMID 37296863, 2023). "DHX9 interacts with cancer-associated genes such as CBP, BRCA1 and EGFR to regulate their transcription and translation." (PMID 37305700, 2023). "An understanding of EGFR activation and signaling is crucial for the therapeutic targeting of this receptor in cancer treatment." (PMID 37660914, 2023). "Sialylation of EGFR has been reported to suppress EGFR dimerization and autophosphorylation and sensitizes cancer cells to Tyrosine Kinase Inhibitors." (PMID 37687086, 2023). "Previous studies have reported the interaction between PTK7 and ROR2, FGFR1, or EGFR in cancer cells." (PMID 37569547, 2023).
cancer (continued). "The in vitro results demonstrated that scFv-OMVs effectively targeted EGFR on the surface of various EGFR high-expressed cancer cells, indicating their potential effectiveness in different types of cancer models." (PMID 37775519, 2023). "We also tested IL2-stimulated NK cells against additional EGFR-positive cancer cells (A549) in presence of ascites and found that malignant ascites suppressed natural cytotoxicity and ADCC." (PMID 37684704, 2023). "It has been described that there are some receptors overexpressed in cancer cells, including transferrin, integrin, folate, EGFR, CD13, monocarboxylate transporter-1 and biotin." (PMID 37284445, 2023). "The process of cancer cell invasion and metastasis involves matrix metalloproteinases (MMPs), which are partially EGFR-regulated." (PMID 37516013, 2023). "To investigate the targeted affinity of LP-S towards EGFR-expressing cancer cells, we employed three OSCC cell lines characterized by varying levels of EGFR expression." (PMID 37736720, 2023). "In this study, we constructed a nomogram prediction model for VTE risk including KPS, stage of cancer, varicosity, COPD, CVC, albumin, PT, leukocyte counts, EGFR-TKI, dexamethasone, and bevacizumab." (PMID 36872336, 2023). "Recent studies have revealed that dysfunctional EGFR signaling promotes the acquisition of cancer stem-like traits by increasing the expression levels of cancer stemness markers in NSCLC." (PMID 37298389, 2023). "For cancers that have genetic changes in epidermal growth factor receptor (EGFR), treatments such as osimertinib have allowed patients to live longer." (PMID 37296959, 2023). "These authors activated EGFR by the addition of EGF ligand or ectopic expression of EGFR in two established cancer cell lines (UMSCC-22B and HN-1)." (PMID 37368660, 2023). "EGFR can be considered a biomarker of cancer aggressiveness, since metastatic cells express five times more EGFR than nonmetastatic cells." (PMID 37853459, 2023). "In this proof-of-concept study, the authors targeted two antibodies (cetuximab and panitumumab) against different members of the epidermal growth factor receptor (EGFR) family, which is overexpressed in many cancers." (PMID 37998152, 2023). "This type of cancer is treated with EGFR tyrosine kinase inhibitors (TKIs); however, the majority of patients acquire resistance due to mutation in EGFR p.T790M." (PMID 36986673, 2023). "In this strategy, a multifunctional gold nanoparticle probe (Apt-Au nanoparticles-Ab) was developed by multi-functionalizing Au nanoparticles with aptamers and anti-EGFR antibodies which was subsequently delivered into EGFR positive cancer cell." (PMID 37520291, 2023). "EGFR is an important glycoprotein for cancer biology with a significant number of glycosylation sites (7–13 N-glycosylations in the extracellular domain); it is highly expressed in different cancers and is considered a proteomic marker." (PMID 37259433, 2023). "The phosphorylation of MCM7 at Tyr-Y600 by EGFR, which promotes the proliferation of cancer cells, facilitates the creation and loading of the MCM complex." (PMID 37594635, 2023). "Clarification of vital molecules in cancer cells exposed to EGFR‐targeted therapeutics will enable us to develop novel therapeutics to overcome such drug resistance." (PMID 37341071, 2023). "Epidermal growth factor receptor is the target of several cancer therapeutics including monoclonal antibodies targeted to the extracellular part of EGFR and small molecule inhibitors of the EGFR kinase." (PMID 37170144, 2023). "A total of 40 patients with EGFR-mutant NSCLC who had cancer progression on osimertinib were assigned to two groups, and received osimertinib in combination with either alisertib, an aurora kinase inhibitor, or sapanisertib, an mTOR inhibitor." (PMID 37296863, 2023).
cancer (continued). "Activation of overexpressed epidermal growth factor receptors (EGFR) in cancer cells can be exploited to enhance cellular uptake of drug delivery systems through macropinocytosis." (PMID 37384827, 2023). "Research efforts have predominantly focused on targeting antigens like HER2 and EGFR, showing promise in various cancers." (PMID 37987250, 2023). "Therapies targeting EGF/EGFR have shown to be beneficial for the management of both cancer and cutaneous wounds." (PMID 37735655, 2023). "PRV-LAV can infect cancer cells via NRP1/EGFR signaling and induce cancer cells apoptosis via ER stress." (PMID 37891570, 2023). "In recent years, epidermal growth factor receptor (EGFR)-targeted agents have primarily been used for cancer treatment." (PMID 38092882, 2023). "E5 can promote cancer cell proliferation by interacting with the epidermal growth factor receptor (EGFR)." (PMID 37375112, 2023). "Conditioned media from particulate matter-treated macrophages increased cancer cell motility and activated EGFR signaling in cancer cells." (PMID 37830596, 2023). "The effects of EGFR knockout on inhibition of cancer cell fusion can be precisely probed at single cell resolution by using the same multifunctional delivery vector to deliver a molecular beacon‐based AND logic gate into fused cells." (PMID 37590231, 2023). "On the contrary, signal transduction pathways associated with GPCR (R‐HSA‐388396), EGFR (R‐HSA‐177929), and MAPK1/MAPK3 signaling (R‐HSA‐5684996) were predominantly downregulated in both aging and cancer." (PMID 37888486, 2023). "The cohort also included cancers with a mix of molecular subgroups [16% epidermal growth factor receptor (EGFR)-positive aNSCLC, 48% RAS-positive mCRC] and sites of disease (e.g. bone, liver, brain)." (PMID 36208697, 2023). "This has been found, for example, for modular nanotransporters for delivering cytotoxic agents into the nuclei of cancer cells with the overexpression of the EGFR or the melanocortin 1 receptor." (PMID 36986848, 2023). "The activation of EGFR has been widely confirmed to significantly promote cancer progression, metastasis, recurrence, and drug resistance." (PMID 38008826, 2023). "Nimotuzumab (NmAb), an anti-EGFR monoclonal antibody (mAb), is used against some of EGFR-overexpressed cancers in various countries." (PMID 37623652, 2023). "Skin biopsies from cancer patients receiving EGFR inhibition therapy show an increase in MHC I protein expression, as well as an increase in MHC I and MHC II allotypes at the RNA level." (PMID 38067396, 2023). "We also showed that HSP90 and SMURF2 maintain stability of wild-type EGFR in cancer cells and tumors." (PMID 37399454, 2023). "NUAK1 was required for the Akt/FOXO1/3a axis, regulating p21CIP1, p27KIP1, and FoxM1 expression and cancer cell survival upon EGFR stimulation." (PMID 38135881, 2023). "The EGFR plays a significant role in cellular survival processes and has been extensively studied as a biomarker in various cancer types, especially OSCC." (PMID 37685910, 2023). "This can include dysfunction of natural killer (NK) cells and macrophages that decrease the anti-EGFR antibody-dependent cellular cytotoxicity, and decreased density of effector T-cells and increased PD-L1 expression which assist cancer survival." (PMID 36979659, 2023). "The effect of EGFR exon-skipping ASOs on the migrating potential of cancer cells was studied using a wound healing assay." (PMID 38137520, 2023). "Coherently, tumors with CBX3 gene amplification display a low gain increase or high-grade amplification of EGFR gene, thus confirming the evidence that CBX3 and EGFR gene amplification co-occurs in diverse human cancers." (PMID 37633946, 2023).